TXNRD1 (thioredoxin reductase 1)
Description:
Reduces disulfide protein thioredoxin (Trx) to its dithiol-containing form. Homodimeric flavoprotein involved in the regulation of cellular redox reactions, growth and differentiation. A selenocysteine residue at the C-terminal active site is essential for catalysis (Probable). Also has reductase activity on hydrogen peroxide (H2O2). [Isoform 1]: Induces actin and tubulin polymerization, leading to formation of cell membrane protrusions. [Isoform 4]: Enhances the transcriptional activity of estrogen receptors ESR1 and ESR2. [Isoform 5]: Enhances the transcriptional activity of the estrogen receptor ESR2 only. Mediates cell death induced by a combination of interferon-beta and retinoic acid.
Synonyms: TR; GRIM-12; TXNR; Trxr1; TXNR1; TR1
Tractability: Small molecule: an approved drug acts on it; a structure with a bound ligand is known; a high-quality ligand is known; it has a high-quality binding pocket; it belongs to a druggable protein family. PROTAC: UniProt records ubiquitination sites on it; ubiquitination databases record sites on it; its protein half-life has been measured; a small molecule that binds it is known.
Target class: Enzyme; Oxidoreductase
Gene: Protein-coding gene on chromosome 12 (104,215,779 to 104,350,307, forward strand). Ensembl gene ENSG00000198431.
Subcellular location: Cytoplasm (Isoform 1); Cytoplasm (Isoform 4); Nucleus; Cytoplasm (Isoform 5)
Subcellular location (Human Protein Atlas): Nucleoplasm
Pathways (Reactome):
Metabolism: Interconversion of nucleotide di- and triphosphates; Metabolism of ingested H2SeO4 and H2SeO3 into H2Se; Metabolism of ingested MeSeO2H into MeSeH; PPARA activates gene expression
Cellular responses to stimuli: Detoxification of Reactive Oxygen Species; NFE2L2 regulating anti-oxidant/detoxification enzymes
Disease: Uptake and function of diphtheria toxin
Gene Ontology:
Molecular function: FAD binding; identical protein binding; NADPH peroxidase activity; protein binding; thioredoxin-disulfide reductase (NADPH) activity; flavin adenine dinucleotide binding; methylseleninic acid reductase activity; methylselenol reductase activity; oxidoreductase activity; oxidoreductase activity, acting on a sulfur group of donors, NAD(P) as acceptor
Biological process: signal transduction; cell redox homeostasis; cellular oxidant detoxification; selenium compound metabolic process
Cellular component: cytoplasm; extracellular exosome; nucleoplasm; nucleus; thioredoxin-disulfide reductase complex; cytosol; mitochondrion
Genetic constraint (gnomAD): Loss-of-function variants: 42 observed, 53.97 expected, observed/expected ratio (o/e) 0.78, 90% interval 0.61 to 1.01. The upper end of that interval is the gene's LOEUF score, 1.01, which puts it in group 4 of 6, group 1 being the genes least tolerant of losing a copy. Missense variants: 623 observed, 682.56 expected, observed/expected ratio (o/e) 0.91, 90% interval 0.85 to 0.98. Synonymous variants: 258 observed, 251.93 expected, observed/expected ratio (o/e) 1.02, 90% interval 0.92 to 1.13.
Homologues: Orthologues: chimpanzee TXNRD1 (99% identical), dog TXNRD1 (86% identical), rabbit TXNRD1 (83% identical), macaque TXNRD1 (78% identical), guinea pig TXNRD1 (70% identical), mouse Txnrd1 (70% identical), pig TXNRD1 (70% identical), tropical clawed frog txnrd1 (68% identical), rat Txnrd1 (65% identical), Caenorhabditis elegans F20D6.11 (16% identical), Drosophila melanogaster CG4199 (15% identical), Drosophila melanogaster CG10700 (14% identical). Paralogues in human: TXNRD3 (64% identical), TXNRD2 (43% identical), GSR (29% identical), DLD (24% identical), AIFM3 (18% identical), AIFM1 (17% identical), PYROXD1 (14% identical).
Diseases named in the same sentence as TXNRD1 in open-access papers:
TXNRD1 is named in the same sentence as 162 diseases in open-access papers, as found by Europe PMC text mining. Sharing a sentence is not in itself a finding about the gene and the disease. The quoted sentences say what the papers report.
breast carcinoma (41 papers, 2010 to 2025). "The overexpression of TXNRD1 was proved to be associated with poor prognosis in breast cancer through an increase in oxidative stresses." (PMID 34741349, 2021). "High expression of TXNRD1 is associated with increased oxidative stress and correlates with poor prognosis in breast cancer." (PMID 31430859, 2019). "Previous analyses of TXNRD1 expression have shown that TXNRD1 is upregulated in pancreatic, colon, lung, prostate, and breast cancers, and is associated with poor cancer prognosis." (PMID 31430859, 2019). "TXNRD1, as a key regulation factor in oxidative stress control, was found to be associated with poor prognosis in breast cancer patients." (PMID 29910195, 2018). "Accordingly, high expression of TXN and TXNRD1 has been previously associated to high grade breast cancers." (PMID 29755668, 2018). "Four SNPs (GPX3 rs2070593, rsGPX4 rs2074451, SELS rs9874, and TXNRD1 rs17202060) significantly interacted with dietary oxidative balance score after adjustment for multiple comparisons to alter breast cancer risk." (PMID 24278290, 2013). "Lower expression of TrxR1/TXNRD1 therefore appears to be linked to the ER-dependent growth of breast cancer." (PMID 23216744, 2012). "Overexpression of TXNRD1 is associated with breast cancer progression." (PMID 31430859, 2019). "Although we hypothesized that DOBS would modify associations with selenoprotein genes, only one SNP in GPX4, SELS, and TXNRD1 that interacted with DOBS remained statistically significantly associated with breast cancer after adjustment for multiple comparisons." (PMID 24278290, 2013). "TXNRD1 expression was suppressed by miR-3614-5p, and the inhibition of TXNRD1 significantly reduced the proliferation and metastatic potential of breast cancer cells following exposure to cadmium." (PMID 38807590, 2024). "TXNRD1 is upregulated in breast cancer, head and neck cancer, and lung cancer, and its overexpression is linked to a bad prognosis." (PMID 37999212, 2023). "In breast cancer, it is likely that miR-526b and miR-655 contribute to the induction of oxidative stress by regulating TXNRD1 expression, the overexpression of which promotes the invasive capacity of breast cancer cells." (PMID 36428665, 2022). "The high expression of both thioredoxin 1 (Trx1) and thioredoxin reductase 1 (TrxR1) is observed in several human cancers, including breast cancer, and the over-expression of Trx1 in MDA-MB-231 breast cancer cell lines promoted an aggressive phenotype." (PMID 36473850, 2022). "TXNRD1 and thioredoxin interacting protein (TXNIP) were associated with poor breast cancer prognosis, and ERBB2 was suggested to play a role in altering their redox control pathway." (PMID 35158912, 2022). "Some reports showed that genetic variations in some selenoproteins, such as GPX1, GPX3, GPX4, SELENOS, and TXNRD1, are correlated to breast cancer development." (PMID 35158912, 2022). "TXNRD1 is increased in head and neck cancer, breast cancer, and lung cancer, and its overexpression is correlative with poor prognosis." (PMID 35127477, 2021). "We found that hypoxia enhanced TXNRD1 expression in all breast cancer cell lines, but the most significant increase was found in MCF7-miR655 cells." (PMID 32707933, 2020). "Since we observed that miRNA overexpression results in the upregulation of TXNRD1 in breast cancer, we further wanted to investigate this mechanism in silico." (PMID 31430859, 2019). "This shows that while miR526b still appeared to be involved in oxidative stress and the TXNRD1 pathway, miR655 has a stronger role in oxidative stress pathways in breast cancer." (PMID 31430859, 2019). "In breast cancer, 17 genes were associated with poor prognosis, such as glucose-6-phosphate dehydrogenase (G6PD), heme oxygenase (decycling) 1 (HMOX1) and thioredoxin reductase 1 (TXNRD1), and only 2 with good outcome." (PMID 24342878, 2013).
breast carcinoma (continued). "Five SNPs, GPX3 rs2070593 (p=0.002), GPX4 rs2074451 (p=0.046), SELS rs9874 (p=0.029), TXNRD1 rs17202060 (p=0.007) and TXNRD2 rs7322262 (p=0.025), significantly interacted with DOBS to alter breast cancer risk." (PMID 24278290, 2013). "In the present study we observed that high expression of TXNRD1 and low expression of TXNIP are associated with worse prognosis in breast cancer." (PMID 20584310, 2010). "TXNRD1 and TXNIP are associated with prognosis in breast cancer, and ERBB2 seems to be one of the factors shifting balances of both factors of the redox control system in a prognostic unfavorable manner." (PMID 20584310, 2010). "High expression of TXN and TXNRD1 with low expression of TXNIP was associated with dysfunctional T cell phenotype and shorter survival of the breast carcinoma cohort and colorectal carcinoma cohort, in accordance with the abnormal expression status of the Trx system in BRCA and COAD." (PMID 39744566, 2025). "Similarly, an overexpression of TXNRD1 in human breast cancer was indicated as an index of cancer progression and associated with poor prognosis." (PMID 35158912, 2022). "Moreover, in breast cancer cells, TXNRD1 overregulation, by inducing epithelial-to-mesenchymal transition (EMT), enhanced invasiveness, thus being considered a candidate for therapeutic targeting." (PMID 35158912, 2022). "In addition, SFN, ECN (erucin) and IBN (1-12 μM) were also found to increase the expression levels of thioredoxin reductase 1 (TrxR1) in human breast cancer (MCF-7) cells." (PMID 31003534, 2019). "Here, we observed that a key regulatory protein of oxidative stress, TXNRD1, is upregulated in highly metastatic and aggressive breast cancer cell lines, which is supported by other studies showing a link between oxidative stress and breast cancer." (PMID 31430859, 2019). "Interestingly, our analysis revealed that TXNRD1, the gene encoding TrxR1, is upregulated and correlates with bad prognosis in pancreatic, colon, HNSCC, lung, prostate, and breast cancers." (PMID 28770020, 2017). "We therefore decided to interrogate the Oncomine database for TXNRD1 expression in breast cancer." (PMID 23216744, 2012). "The purpose of this work was to study the prognostic influence in breast cancer of thioredoxin reductase 1 (TXNRD1) and thioredoxin interacting protein (TXNIP), key players in oxidative stress control that are currently evaluated as possible therapeutic targets." (PMID 20584310, 2010). "Moreover, TXNRD1 overexpression has been reported in many human malignancies and functions as a prognostic factor for many tumors, such as oral squamous cell carcinomas, lung cancer, breast cancer, astrocytomas, and hepatocellular carcinoma." (PMID 32327612, 2020). "NRF2 knockdown had a pronounced effect on gene expression in MDA-MB-436 breast cancer cells, notably reducing multiple anti-ferroptosis genes, including SLC7A11, NQO1, TXNRD1, GCLM, and AKR1C1." (PMID 40867343, 2025). "SSBP1, TXNRD1, SLC25A5, DDOST, SEH1L, and MCM2 had a significant effect in at least 50% of breast cancer cell lines in the CRISPR-Cas9 and/or RNAi screening data." (PMID 37445737, 2023). "Thioredoxin reductase 1 protein (TXNRD1), glutathione pathway and superoxide dismutase are predominantly and commonly regulated in breast cancer." (PMID 36505465, 2022). "To better understand the interrelation of TXNRD1 and TXNIP with biologically relevant processes in breast cancer, we compared their expression levels with previously published metagenes." (PMID 20584310, 2010). "In order to understand the role of TXNRD1 and TXNIP for the natural history of breast cancer it seemed relevant to focus on untreated patients, because the thioredoxin system has been reported to influence sensitivity of tumor cells to chemotherapy." (PMID 20584310, 2010). "Finally, we used a breast epithelial cell line MCF10A and breast cancer cell lines T47D, MCF7, SKBR3, MCF7-COX2, Hs578T, and MDA-MB-231 to measure TXNRD1 expression." (PMID 31430859, 2019).
breast carcinoma (continued). "Udler did not observe a significant association between any of the TXNRD1 or TXNRD2 SNPs and breast cancer survival." (PMID 24278290, 2013). "Interestingly, the study found that Thioredoxin Reductase 1 (TR1) is downregulated at the mRNA and protein level under conditions of hypoxia in two different cell types (EMT6 breast cancer cells and DT6 transformed fibroblasts)." (PMID 23091723, 2012). "Overall, considering both the CCLE and LINCS datasets, eight selenoproteins were overexpressed (DIO2, GPX1, GPX4, SELENOI, SELENON, SELENOS, TXNRD1 and TXNRD3) and five were down-expressed (DIO1, GPX2, GPX3, SELENOP and SELENOW) in TNBC compared to all other “non-TNBC” breast cancer subtypes." (PMID 35158912, 2022).
lung carcinoma (35 papers, 2015 to 2026). "TrxR1 (Thioredoxin reductase 1) is overexpressed in several types of cancer, containing lung cancer, which is closely linked to metastasis." (PMID 40498096, 2025). "Correlation analysis revealed that auranofin IC50 values were significantly correlated with TXNRD enzymatic activity levels in lung cancer cell lines (r = 0.78, P = 0.007), demonstrating that endogenous TXNRD1 levels in tumor cells are inversely associated with auranofin's activity." (PMID 26657290, 2016). "The results showed that the expression of TXN and TXNRD1 was higher in most lung cancer cell lines than in the normal lung epithelial cell line Beas-2b, while the opposite was observed for TXNIP." (PMID 39744566, 2025). "To further investigate the role of the Trx system in cancer, we used small interfering RNAs (siRNAs) to knock down TXN and TXNRD1 in lung cancer cell lines." (PMID 39744566, 2025). "In this study, we assessed the effectiveness of lenvatinib combined with thioredoxin reductase 1 (TrxR1) inhibitors in human lung cancer cells." (PMID 38164168, 2024). "For instance, shikonin inhibits thioredoxin reductase 1 (TRXR1), thereby inhibiting the reduction of GSSG to GSH, causing apoptosis of gefitinib-resistant lung cancer cells." (PMID 38982494, 2024). "Piperlongumine, an alkaloid derived from long pepper (Piper longum L.), exhibits anticancer activity in lung cancer cells by targeting the glutathione regeneration enzyme, thioredoxin reductase 1 (TXNRD1)." (PMID 38239395, 2023). "Thioredoxin reductase (TXNRD1) is overexpressed in lung cancer cells to maintain tumor survival, and this overexpression has been shown to be associated with clinical outcomes." (PMID 34630529, 2021). "Studies have shown that using small interfering RNAs to knock down thioredoxin reductase 1 (TXNRD1) expression increases the basal level of reactive oxygen species and increases the sensitivity of lung cancer cells to radiotherapy." (PMID 33988228, 2021). "Western blot analysis revealed that lung cancer cells that were highly sensitive to auranofin all expressed low levels of TXNRD1, whereas lung cancer cells with high TXNRD1 levels were relatively resistant to auranofin." (PMID 26657290, 2016). "The targeted removal of TXNRD1 in a mouse lung cancer cell line, LLC1 cells, resulted in the cells reversing many of their malignant properties to those more similar to normal cells, including a dramatic reduction in tumorigenic and metastatic properties." (PMID 26569310, 2015). "siRNA-mediated knockdown of TXN and TXNRD1 inhibited cell proliferation of lung cancer cells." (PMID 39744566, 2025). "GSR depletion renders human lung cancer cells more sensitive to TXNRD1 inhibitor-Auranofin." (PMID 36635256, 2023). "In A549 human lung cancer cells, maintained in growth medium supplemented with 100 nM sodium selenite for optimal selenoprotein saturation and TXNRD1 activity, a clear dose-dependent suppression in RX1 signal was seen with RSL3 and ML162 concentrations of 0.5 μM or higher, but not with ML210." (PMID 37087975, 2023). "TXNRD1-deficient A549 human lung cancer cells, however, were found to have only minor changes in growth properties compared to control TXNRD1-sufficient cells, but no other apparent phenotypic alterations." (PMID 26569310, 2015). "The data suggested that the reduction in TXNRD1 levels in lung cancer cells is anti-tumorigenic." (PMID 26569310, 2015). "Intriguingly, we discovered that lung cancer patients with high levels of TXN and TXNRD1 expression had shorter survival duration and dysfunctional T cell phenotype." (PMID 39744566, 2025).
lung carcinoma (continued). "Our recent study revealed that TXNRD1 siRNA and its inhibitor auranofin were synthetically lethal with the novel AKT inhibitor MK2206 in lung cancer cells and dramatically enhanced the efficacy of MK2206 in both in vitro and in vivo models." (PMID 26657290, 2016). "Treatment of ABC1 and SW900 lung cancer cells, which both contain a functional KEAP1-NRF2 response, resulted in significant induction of NRF2 target gene expression, including NQO1, GCLC, HMOX1 and TXNRD1." (PMID 40890297, 2025). "One study found that EVs derived from human umbilical cord mesenchymal stem cells (hUCMSCs-EVs) could transfer miR-130b-3p into lung cancer cells and promote the occurrence and development of lung cancer through the FOXO3/NFE2L2/TXNRD1 axis." (PMID 35860555, 2022). "Previous studies have revealed that overexpression of TXNRD1 modulates drug-specific cytotoxic responses and inhibition of the TXNRD1 enhances the efficacy of some chemotherapeutics, such as improving ibrutinib’s anti-EGFR activity in lung cancer." (PMID 36319631, 2022). "This was in contrast to their target mRNA expressions (TXNRD1 and HOXA1), thus providing a molecular link between air pollution and non-smoker lung cancer." (PMID 41329722, 2025).